RAB11FIP5 (RAB11 family interacting protein 5)
Description:
Rab effector involved in protein trafficking from apical recycling endosomes to the apical plasma membrane. Involved in insulin granule exocytosis. May regulate V-ATPase intracellular transport in response to extracellular acidosis.
Synonyms: Rab11-FIP5; Gaf-1; GAF1; KIAA0857; RIP11; pp75
Tractability: Antibody: its Gene Ontology location is reachable by antibodies, with high confidence; UniProt places it where antibodies can reach, with medium confidence. PROTAC: ubiquitination databases record sites on it; its protein half-life has been measured.
Gene: Protein-coding gene on chromosome 2 (73,073,382 to 73,156,721, reverse strand). Ensembl gene ENSG00000135631.
Subcellular location: Cytoplasm; Recycling endosome membrane; Early endosome membrane; Golgi apparatus membrane; Cytoplasmic vesicle, secretory vesicle membrane; Mitochondrion membrane
Subcellular location (Human Protein Atlas): Basal body; Centriolar satellite; Vesicles; Acrosome; Annulus; End piece; Primary cilium; Principal piece
Gene Ontology:
Molecular function: gamma-tubulin binding; protein binding; small GTPase binding
Biological process: cellular response to acidic pH; negative regulation of adiponectin secretion; regulation of protein localization to cell surface; insulin secretion involved in cellular response to glucose stimulus; regulated exocytosis
Cellular component: mitochondrial outer membrane; early endosome; Golgi apparatus; mitochondrion; phagocytic vesicle; recycling endosome; secretory granule; cytoplasm; early endosome membrane; Golgi membrane; mitochondrial membrane; recycling endosome membrane; transport vesicle membrane
Genetic constraint (gnomAD): Loss-of-function variants: 48 observed, 72.21 expected, observed/expected ratio (o/e) 0.66, 90% interval 0.53 to 0.85. The upper end of that interval is the gene's LOEUF score, 0.85, which puts it in group 3 of 6, group 1 being the genes least tolerant of losing a copy. Missense variants: 1,474 observed, 1,459.2 expected, observed/expected ratio (o/e) 1.01, 90% interval 0.97 to 1.05. Synonymous variants: 725 observed, 646.06 expected, observed/expected ratio (o/e) 1.12, 90% interval 1.05 to 1.19.
Homologues: Orthologues: chimpanzee RAB11FIP5 (99% identical), macaque RAB11FIP5 (89% identical), pig RAB11FIP5 (84% identical), dog RAB11FIP5 (82% identical), rat Rab11fip5 (74% identical), mouse Rab11fip5 (74% identical), rabbit RAB11FIP5 (73% identical), tropical clawed frog rab11fip5 (37% identical), zebrafish rab11fip5b (18% identical), zebrafish rab11fip5a (18% identical), Drosophila melanogaster Rip11 (12% identical), Caenorhabditis elegans rfip-2 (8% identical). Paralogues in human: RAB11FIP1 (22% identical), RAB11FIP2 (13% identical).
Diseases named in the same sentence as RAB11FIP5 in open-access papers:
RAB11FIP5 is named in the same sentence as 2 diseases in open-access papers, as found by Europe PMC text mining. Sharing a sentence is not in itself a finding about the gene and the disease. The quoted sentences say what the papers report.
autism (2 papers, 2017 to 2021). Persistent deficits in social interaction and communication and interaction as well as a markedly restricted repertoire of activity and interest as well as repetitive patterns of behavior. "It is interesting to consider that, like Rab11fip5, the ablation or reduction of other autism-related gene products leads to reduced telencephalon development in the Xenopus model system, even though the cellular processes regulated by these genes varies considerably." (PMID 33462110, 2021). "Additionally, the autism candidate gene Rab11fip5 was upregulated in our proteome data and plays a role in recycling endosome protein trafficking and neurotransmitter release." (PMID 29090078, 2017).
autism spectrum disorder (1 paper, 2021). A spectrum of developmental disorders that includes autism, and Asperger syndrome. "Interestingly, one such developmental condition in which Rab11fip5 has been reported to play a role is autism spectrum disorders in humans." (PMID 33462110, 2021). "Rab11fip5 is involved in many cellular processes, such as cytoskeleton rearrangement, iron uptake and exocytosis in neuroendocrine cells, and is also known as a candidate gene for autism-spectrum disorder." (PMID 33462110, 2021).